FABP5 (fatty acid binding protein 5)
Diseases named in the same sentence as FABP5 in open-access papers (continued):
Sharing a sentence is not in itself a finding about the gene and the disease.
prostate carcinoma (continued). "First, we demonstrate that FABP5 is among the most frequently amplified genes in human prostate cancer." (PMID 38201488, 2023). "Second, our research shows that the RapidCaP-derived RCaP cells can be used as proxies for ADT- and taxane-resistant human prostate cancer cells and that they are sensitive to FABP5 inhibitors in vitro and in vivo." (PMID 38201488, 2023). "FABP5 amplification and surge in expression are strongly correlated to that of the MYC oncogene, a known driver of advanced PTEN-deficient prostate cancer." (PMID 38201488, 2023). "The emergence of novel targets such as fatty-acid binding protein 5 (FABP5) also illustrates the progress that has been made in the field of prostate cancer." (PMID 35204665, 2022). "Evidently, it was recently revealed that FABP5 upregulates the expression of VEGF in prostate cancer, a key factor that promotes angiogenesis and metastasis as well as RVD." (PMID 35454958, 2022). "In prostate cancer (PC), fatty acid-binding protein 5 (FABP5) resulted as the potential significant exosomal-encapsulated protein in PC patients when compared to controls." (PMID 35047512, 2021). "One study stated the overexpression of FABP5 in prostate cancer cells can be attributed to hypomethylation of the CpG island in its promoter region, along with up-regulation of the direct trans-acting factors Sp1 (specificity protein 1) and c-Myc." (PMID 32579175, 2020). "Experimental assays demonstrated that suppression of FABP5 is accompanied by tumor mass reduction and abrogation of metastasization in prostate cancer." (PMID 32856199, 2020). "In fact, a number of recent studies have confirmed the promoting role of PPARγ in malignant progression of prostate cancer and that the stimulation produced by FABP5- transported fatty acids plays an important role in PPARγ activation." (PMID 31258834, 2019). "Previous work has suggested that the dependency of the prostate cancer cells on the FABP5-related pathway is increased gradually with a concomitant reduction in dependency on the AR-initiated pathway, until the former becomes completely dominant." (PMID 31258834, 2019). "In particular, compound 1 suppressed the gene expression of fatty acid-binding protein 5 (FABP5), which is involved in promoting cell proliferation and metastasis in prostate cancer cells." (PMID 31427660, 2019). "Prostate cancer (PCa) is defined by dysregulated lipid signaling and is characterized by upregulation of lipid metabolism-related genes including fatty acid binding protein 5 (FABP5), fatty acid synthase (FASN), and monoacylglycerol lipase (MAGL)." (PMID 31831821, 2019). "A recent investigation reported upregulation of VEGF in response to a FABP5-dependent activation of PPARγ as a crucial event in tumor neovascularization of prostate cancers." (PMID 31143113, 2019). "After FABP5 had been shown to promote malignant progression in prostate cancer cells, its increased expression in archival prostate cancer tissues was found to be significantly associated with reduced patient survival times." (PMID 31258834, 2019). "Stable knockdown of FABP5 in prostate cancer cells significantly reduced the tumor burden in a xenograft mouse model, highlighting the significance of lipid uptake to tumor growth in vivo." (PMID 31769430, 2019). "Of the fatty acid binding proteins (FABPs) present in mammalian tissues, FABP4 and cutaneous FABP (FABP5) have been extensively studied in prostate cancer." (PMID 29181019, 2017). "The present study showed the high expression of FABP5 in EVs from patients with high GS prostate cancer." (PMID 28211531, 2017). "FABP5, whose expression is directly regulated by PPARβ/δ, binds fatty acids that serve as ligands for PPARγ and enhances prostate cancer cell proliferation." (PMID 29181019, 2017).
prostate carcinoma (continued). "In contrast to numerous studies conducted to investigate the crucial role of fatty acid binding protein 5 (FABP5) in prostate cancer, investigations on the possible involvement of other FABPs are rare." (PMID 27779102, 2016). "Recently, it was established that cancer promoting activity of FABP5 is closely related to its ability to bind and transport extracellular fatty acids to their nuclear receptors in prostate cancer cells." (PMID 26814431, 2016). "In contrast, increasing FABP5 expression in the weakly malignant prostate cancer cell line LNCaP promoted their invasiveness and proliferation rate in vitro and increased their tumorigenicity in vivo." (PMID 26814431, 2016). "Conversely, invasion capacity and tumor growth were significantly reduced in prostate cancer cells with reduced FABP5 expression." (PMID 25866768, 2015). "Despite this, increased expression of FABP5 in prostate cancer cells increased fatty acid uptake and peroxisome proliferator-activated receptor gamma (PPARγ) expression which enhanced tumor progression." (PMID 25866768, 2015). "Down-regulation of FABP5 by FABP5-specific siRNA effectively inhibited prostate cancer cell growth in nude mice." (PMID 22043320, 2011). "FABP5, which encodes cutaneous fatty acid binding protein (C-FABP), is up-regulated in prostate cancer and acts as a putative oncogene." (PMID 22043320, 2011). "We show here that expression levels of both FABP5 and PPARβ/δ are correlated with the tumorigenic potential of prostate cancer cell lines." (PMID 20847935, 2010). "The data presented above demonstrate that FABP5, which functions to selectively deliver ligands to the nuclear receptor PPARβ/δ, is under the direct control of its cognate nuclear receptor in prostate cancer cells." (PMID 20847935, 2010). "We show further that activation of the FABP5/PPARβ/δ pathway enhances the proliferation of malignant prostate cancer cell line PC3M, and that downregulation of either protein inhibits the growth of these cells." (PMID 20847935, 2010). "The resulting positive-feedback loop augments the overall activity of the FABP5/PPARβ/δ pathway, leading to efficient induction of PPARβ/δ target genes involved in cell proliferation and survival and supporting prostate cancer cell growth." (PMID 20847935, 2010). "It was also reported that FABP5 can serve as a prognostic marker and that it induces metastasis of prostate cancer." (PMID 20847935, 2010). "In addition, it has been demonstrated that FABP5 inactivation suppresses PCa growth and sensitizes prostate cancer cells to drugs targeting microtubules, leading to cell death." (PMID 41374926, 2025). "In vitro studies have demonstrated that genetic knockdown or silencing of FABP5 inhibits prostate cancer cell proliferation and invasiveness and that inhibitors targeting FABP5 exert synergistic effects with taxanes, leading to decreased tumor growth and metastasis." (PMID 39823981, 2025). "Additionally, FABP5 overexpression promotes prostate cancer growth and proliferation, likely by enhancing the activity of intracellular receptors such as PPAR-γ." (PMID 39823981, 2025). "In addition, siRNA-induced depletion of FABP5 in a prostate cancer cell line substantially inhibited tumorigenicity and proliferation in nude mice." (PMID 39273233, 2024). "Moreover, silencing FABP5 has been found to decrease the proliferation of prostate cancer cells in vitro and in vivo." (PMID 36792587, 2023). "Similarly, in our meta-analysis, fatty acid-binding protein 5 (FABP5) emerged as a key player in prostate cancer and has been explored as a potential biomarker." (PMID 38201450, 2023). "In addition, FABP5 was highly expressed in prostate cancer, intrahepatic cholangiocarcinoma, colorectal cancer, cervical cancer, and other tumor tissues, while was low expressed in normal tissues." (PMID 34632074, 2021).
prostate carcinoma (continued). "An experimental study performed on mouse xenografts suggested that atelocollagen-delivered siRNA targeting the FABP5 gene could be applied as the therapy for prostate cancer." (PMID 32579175, 2020). "FABP5 knockdown was shown to inhibit tumor cell proliferation and invasiveness of cervical cancer cells and oral squamous cell carcinoma as well as tumor cell proliferation of prostate cancer cells." (PMID 31143113, 2019). "Another report described upregulation of FABP5 in malignant prostate cancer versus normal tissue." (PMID 31769430, 2019). "Thus, when FABP5 expression is increased, excessive amounts of fatty acids are transported into the nucleus of the prostate cancer cells, where they act as signalling molecules to stimulate their nuclear receptor PPARγ." (PMID 31258834, 2019). "FABP5 might play a pivotal role in fatty acid metabolism as a lipid transporter and/or an important regulatory factor for lipid metabolism in prostate cancer cells." (PMID 31427660, 2019). "We studied FABP5 expression in prostate cancer cell lines and prostate cancer tissues." (PMID 28211531, 2017). "Next, we determined whether FABP5 in urinary EVs after massage could predict prostate cancers with GS of 7 or more, which requires definitive treatment, in the cohort without metastasis (n = 26)." (PMID 28211531, 2017). "In addition, cooperation between FABP5 and PPARβ/δ has been shown to enhance cell survival and proliferation in prostate cancer cells." (PMID 28542209, 2017). "FABP5 in EVs from high GS prostate cancer may affect the endothelial cells in tumor microenvironments or in distant areas and promote the metastasis of prostate cancer." (PMID 28211531, 2017). "Although androgen can modulate VEGF expression through Sp1/Sp3 binding site on VEGF promoter in androgen-dependent prostate cancer cells, this route, disappeared as the cells gradually lost their androgen dependency; was replaced by the FABP5-PPARγ-VEGF signalling pathway." (PMID 26814431, 2016). "To investigate the molecular mechanisms involved in the malignant progression of prostate cancer cells and to identify possible novel markers, we characterised the role of FABP5 and demonstrated its crucial function in promoting tumorigenicity and metastasis of prostate cancer." (PMID 27779102, 2016). "Thus suppression of FABP5 expression in a highly malignant prostate cancer cell line PC3-M significantly reduced their invasiveness in vitro and inhibited their tumorigenicity in vivo by reducing the level of VEGF and microvessel densities." (PMID 26814431, 2016). "FABP5 played a crucial promoting role in tumorigenicity and metastasis of prostate cancer." (PMID 27779102, 2016). "In previous work, it is suggested that the excessive amount of fatty acids transported by FABP5 may facilitate the malignant progression of prostate cancer cells through a FABP5-PPARγ-VEGF signal transduction axis to increase angiogenesis." (PMID 26814431, 2016). "Although it has been suggested that the increased FABP5 may interact with the increased level of PPARγ in a coordinated way to facilitate malignant progression of prostate cancer cells, the exact role of PPARγ in tumorigenicity of prostate cancer is not clear." (PMID 26814431, 2016). "FABP5 was first identified in psoriatic lesions, was linked to metastasis in 2000 where FABP5 mRNA was expressed in metastatic breast and prostate cancer cell lines compared to non-metastatic cell lines." (PMID 25779666, 2015). "The data reveal the existence of a positive feedback loop that enhances the transcriptional activities of the FABP5/PPARβ/δ pathway in prostate cancer cells, and they indicate that these activities support prostate carcinoma cell proliferation and tumorigenicity." (PMID 20847935, 2010). "In turn, in prostate cancer cells, activated PPARβ/δ upregulates the expression of FABP5." (PMID 20847935, 2010).
prostate carcinoma (continued). "Furthermore, the data show that downregulation of either FABP5 or PPARβ/δ inhibits the growth of the highly malignant prostate cancer PC3M cells." (PMID 20847935, 2010). "Thus, the CRABP-II promoter harbors a consensus RARE, the expression of FABP4 is directly regulated by PPARγ in adipocytes, and, as shown here, FABP5 is a direct target gene for PPARβ/δ in prostate cancer cells." (PMID 20847935, 2010). "The present study was undertaken in order to examine whether FABP5 and PPARβ/δ are involved in regulation of prostate cancer cell growth and to obtain insight into mechanisms by which the expression of FABP5 is regulated." (PMID 20847935, 2010). "GW0742 induced the expression of FABP5 both in the absence and in the presence of cycloheximide, indicating that the effect did not require de novo protein synthesis raises the possibility that FABP5 is a direct target gene for PPARβ/δ in PC3M prostate cancer cells." (PMID 20847935, 2010). "Similarly, activated PPARβ/δ effectively upregulates FABP5 expression in prostate cancer cells but has little effect on the expression of the gene in adipocytes (our unpublished observations)." (PMID 20847935, 2010). "Thus, several studies have reported that FABP5 was upregulated in cholangiocarcinoma and hepatocellular carcinoma, prostatic carcinoma, glioma, oral squamous cell carcinoma, cervical cancer, colorectal cancer, pancreatic cancer, non-small cell lung cancer, breast cancer." (PMID 38965292, 2024). "Thus FABP5 is now a valuable prognostic factor for advanced prostate cancer." (PMID 31258834, 2019). "FABP5 might be responsible for fatty acid metabolism as a lipid transporter and/or an important regulatory factor, suggesting that its critical role in metabolic alterations of fatty acid metabolism in prostate cancer." (PMID 28798415, 2017). "FABP5 in urinary EVs could be a potential biomarker of high GS prostate cancer." (PMID 28211531, 2017). "After FABP5 was proven to be a prognostic marker and potential treatment target, a frequently asked question was whether other FABP family proteins were also diagnostic or prognostic markers for prostate cancer." (PMID 27779102, 2016). "Thus combining current results with those of the past suggested that FABP5 and PPARγ may be functioning in a coordinated manner to promote the malignant progression of human prostate cancer cells." (PMID 26814431, 2016). "FABP5 inhibitors, such as the chemical inhibitors SBFI-26, SBFI-102, and SBFI-103, can inhibit malignant progression of prostate cancer." (PMID 40694956, 2025). "Fatty acid-binding protein 5 (FABP5) promoted lipolysis droplets, de-novo fatty acid synthesis, and coordinated lipid signaling that promoted prostate cancer metastasis." (PMID 35351947, 2022). "Western blot analysis showed that FABP5 was expressed in EVs from the supernatants of PC3 and DU145 prostate cancer cell lines." (PMID 28211531, 2017). "Androgen-independent prostate cancer cell line PC3-M, expressing high levels of FABP5 and PPARγ was an extremely malignant and metastatic cell line." (PMID 28415688, 2017). "Furthermore (right), we found that FABP5 high mRNA expression is significantly correlated with MYC gene amplification, a well-validated driver gene of prostate cancer." (PMID 38201488, 2023). "In the present study, we have clearly revealed that FABP5 activated expression of metabolic genes (ATP5B, LCHAD, ACO2, FH and MFN2) via a novel signaling pathway in an ERRα (estrogen-related receptor α)-dependent manner in prostate cancer cell lines." (PMID 30167092, 2018). "Immunohistochemical analysis of prostatectomy specimens from the patients with prostate cancer showed that prostate cancer cells with Gleason pattern 4 were stained with anti-FABP5 antibody in contrast to the negative normal epithelium." (PMID 28211531, 2017).
prostate carcinoma (continued). "To further functionally characterise the FABP5-PPARγ-VEGF signal transduction pathway, we have, in this work, investigated the molecular mechanisms involved in its tumorigenicity promoting role in prostate cancer." (PMID 26814431, 2016). "Previously, FABP5 mRNA was found to be overexpressed in metastatic breast and prostate cancer cell lines compared to non-metastatic cell lines." (PMID 25779666, 2015). "Further characterizing FABP5 and TARP, they are rearranged in ERG0 samples, which means that these two genes could be used to define distinct group of prostate cancer." (PMID 22811706, 2012). "Among them, fatty acid binding protein 5 (FABP5), Alpha-1-Microglobulin/Bikunin Precursor (AMBP), Charged Multivesicular Body Protein 4A (CHMP4A), and Charged Multivesicular Body Protein 4C (CHMP4C) were significantly differentially expressed in prostate cancer patients compared to normal samples." (PMID 38201450, 2023). "However, only FABP5 was significantly overexpressed in EVs in men with prostate cancer compared to men with negative biopsy in the verification cohort." (PMID 28211531, 2017). "Although functional characterisation work and other studies demonstrated that FABP5 and other FABPs may be prognostic markers and treatment targets for different cancer types, the potential involvement of other FABPs in malignant progression of prostate cancer had not been fully investigated." (PMID 27779102, 2016). "The experimental treatment established in this study is based on the recent discovery that it is the FABP5-PPARγ-VEGF signalling axis, rather than the androgen receptor pathway, played a dominant role in promoting the malignant progression of castration resistant prostate cancer cells." (PMID 28415688, 2017).